TMPRSS9 (transmembrane serine protease 9)
Description:
Serase-1 and serase-2 are serine proteases that hydrolyze the peptides N-t-Boc-Gln-Ala-Arg-AMC and N-t-Boc-Gln-Gly-Arg-AMC. In contrast, N-t-Boc-Ala-Phe-Lys-AMC and N-t-Boc-Ala-Pro-Ala-AMC are not significantly hydrolyzed.
Tractability: Antibody: UniProt places it where antibodies can reach, with high confidence; UniProt predicts a signal peptide or a membrane-spanning region; its Gene Ontology location is reachable by antibodies, with medium confidence.
Gene: Protein-coding gene on chromosome 19 (2,360,238 to 2,426,261, forward strand). Ensembl gene ENSG00000178297.
Subcellular location: Cell membrane
Gene Ontology:
Molecular function: serine-type peptidase activity; serine-type endopeptidase activity
Biological process: plasminogen activation; proteolysis
Cellular component: plasma membrane
Genetic constraint (gnomAD): Loss-of-function variants: 113 observed, 99.66 expected, observed/expected ratio (o/e) 1.13, 90% interval 0.97 to 1.33. The synonymous counts are far from expectation, so gnomAD's model fits this gene poorly and the ratio says little. Missense variants: 1,759 observed, 1,394.3 expected, observed/expected ratio (o/e) 1.26, 90% interval 1.21 to 1.31. Synonymous variants: 788 observed, 605.34 expected, observed/expected ratio (o/e) 1.3, 90% interval 1.23 to 1.38.
Homologues: Orthologues: macaque TMPRSS9 (95% identical), chimpanzee TMPRSS9 (90% identical), mouse Tmprss9 (80% identical), pig TMPRSS9 (79% identical), rat Tmprss9 (79% identical), dog TMPRSS9 (78% identical), guinea pig TMPRSS9 (70% identical), tropical clawed frog tmprss9 (57% identical), zebrafish tmprss9 (29% identical), Drosophila melanogaster Sb (11% identical), Drosophila melanogaster CG17242 (5% identical). Paralogues in human: ST14 (15% identical), TMPRSS6 (14% identical), TMPRSS7 (13% identical), TMPRSS15 (12% identical), TMPRSS5 (12% identical), TMPRSS11E (11% identical), HPN (11% identical), TMPRSS2 (11% identical), TMPRSS3 (11% identical), TMPRSS13 (11% identical), PRSS21 (9% identical), TMPRSS11D (9% identical), and 5 more.
Diseases named in the same sentence as TMPRSS9 in open-access papers:
TMPRSS9 is named in the same sentence as 6 diseases in open-access papers, as found by Europe PMC text mining. Sharing a sentence is not in itself a finding about the gene and the disease. The quoted sentences say what the papers report.
autism spectrum disorder (2 papers, 2021 to 2025). A spectrum of developmental disorders that includes autism, and Asperger syndrome. "A Tmprss9 KO targeting exon 2 recently suggested an association to autism spectrum disorders and, a borderline recognition memory deficit was found in aged female, but not in aged male or younger mice." (PMID 40652049, 2025). "To date, TMPRSS9 variants have been only reported in a single patient with autism spectrum disorders, who was a compound heterozygote for 2 frameshift mutations." (PMID 34758722, 2021).
influenza (1 paper, 2017). An acute viral infection of the respiratory tract, occurring in isolated cases, in epidemics, or in pandemics; it is caused by serologically different strains of viruses (influenzaviruses) designated A, B, and C, has a 3-day incubation period, and usually lasts for 3 to 10 days. "We also identified two novel host factors, CTSC and TMPRSS9, which have not previously been reported to be associated with influenza replication and represent opportunities for future study." (PMID 28272419, 2017).
infection (1 paper, 2023). The state of being infected such as from the introduction of a foreign agent such as serum, vaccine, antigenic substance or organism. "As the infection progressed, an increase in F protein cleavage was observed in the rTS-2B/GFP- and rTS-GFP-infected cells expressing Tmprss9." (PMID 37042750, 2023). "At 72 h post infection (hpi), the different levels of rTS-2B/GFP titers from the cells expressing proteases were observed in the order of Tmprss9 > Cfd > Prss23 = Tmprss4 > F7 > ev, and those of rTS-GFP titers were observed in the order of Tmprss9 > Tmprss4 > F7 > ev = Cfd = Prss23." (PMID 37042750, 2023).
TMPRSS9 also shares sentences with these, for which no sentence is quoted: tumor (2 papers); COVID-19 (1); neurodevelopmental disorder (1).